B3GALT5 (beta-1,3-galactosyltransferase 5)
Description:
Catalyzes the transfer of Gal to GlcNAc-based acceptors with a preference for the core3 O-linked glycan GlcNAc(beta1,3)GalNAc structure. Can use glycolipid LC3Cer as an efficient acceptor.
Synonyms: Beta-1,3-GalTase 5; Beta3Gal-T5; B3GalT-V; GLCT5; B3T5; B3GalTx; beta-3-Gx-T5
Tractability: Antibody: UniProt predicts a signal peptide or a membrane-spanning region.
Target class: Enzyme; Transferase
Gene: Protein-coding gene on chromosome 21 (39,556,442 to 39,673,137, forward strand). Ensembl gene ENSG00000183778.
Subcellular location: Golgi apparatus membrane
Pathways (Reactome):
Metabolism: Lewis blood group biosynthesis
Gene Ontology:
Molecular function: protein binding; N-acetyl-beta-D-glucosaminide beta-(1,3)-galactosyltransferase activity; hexosyltransferase activity
Biological process: glycoprotein biosynthetic process; oligosaccharide biosynthetic process; carbohydrate derivative metabolic process
Cellular component: endoplasmic reticulum; Golgi apparatus; Golgi membrane; membrane
Genetic constraint (gnomAD): Loss-of-function variants: 0 observed, 0.28 expected, observed/expected ratio (o/e) 0, 90% interval 0 to 1.87. That is too few expected variants to judge how well the gene tolerates losing a copy. Missense variants: 302 observed, 363.24 expected, observed/expected ratio (o/e) 0.83, 90% interval 0.76 to 0.92. Synonymous variants: 149 observed, 145.74 expected, observed/expected ratio (o/e) 1.02, 90% interval 0.89 to 1.17.
Homologues: Orthologues: chimpanzee B3GALT5 (98% identical), macaque B3GALT5 (92% identical), dog B3GALT5 (77% identical), mouse B3galt5 (72% identical), rat B3galt5 (71% identical), rabbit B3GALT5 (70% identical), guinea pig B3GALT5 (67% identical), tropical clawed frog b3galt5.2 (47% identical), tropical clawed frog b3galt5l (47% identical), tropical clawed frog b3galt5.4 (47% identical), tropical clawed frog b3galt5.3 (46% identical), zebrafish b3galt10.1 (32% identical), and 6 more. Paralogues in human: B3GALT1 (38% identical), B3GALT2 (37% identical), B3GALNT1 (36% identical), B3GNT5 (30% identical), B3GALT4 (29% identical), B3GNT3 (28% identical), B3GNT4 (28% identical), B3GNT6 (28% identical), B3GNT7 (28% identical), B3GNT9 (28% identical), B3GALT9 (27% identical), B3GNT2 (26% identical), and 3 more.
Diseases named in the same sentence as B3GALT5 in open-access papers:
B3GALT5 is named in the same sentence as 25 diseases in open-access papers, as found by Europe PMC text mining. Sharing a sentence is not in itself a finding about the gene and the disease. The quoted sentences say what the papers report.
breast carcinoma (8 papers, 2020 to 2024). "High B3GALT5 expression is associated with tumor progression and the metastasis of breast cancer, and may lead to a poor prognosis for patients with breast cancer." (PMID 36544490, 2022). "In our previous study, we conducted an invasion assay to assess the role of globo-series glycosphingolipids and β3GalT5 in breast cancer." (PMID 39769120, 2024). "The function of the B3GALT5 protein is most well-studied in colon, pancreatic and breast cancers, in which B3GALT5 catalyzes the synthesis of the sialyl Lewis-a antigen." (PMID 36995257, 2023). "Taken together, these findings suggest that B3GALT5 plays a key role in the migration and invasion ability in breast cancer." (PMID 33413566, 2021). "We further conducted univariate and multivariate Cox proportional hazard regression analyses to assess the impact of the expression levels of B3GALT5 on breast cancer recurrence and patient survival." (PMID 33413566, 2021). "Taken together, the results indicated the adverse prognostic significance of high expression of B3GALT5 in breast cancer, especially for patients with early stage hormonal receptor positive tumors." (PMID 33413566, 2021). "To date, there is only one report showing B3GALT5 expression in breast carcinoma tissues as determined by immunohistochemistry (IHC) positively correlated with the stages and poor disease-free survival." (PMID 33413566, 2021). "To explore the clinical relevance of B3GALT5 expression in breast cancers, we performed qRT-PCR analysis to examine B3GALT5 mRNA expression levels in tumor and adjacent non-tumor tissues obtained from 202 breast cancer patients." (PMID 33413566, 2021). "Here we showed significant higher expression of B3GALT5 in TNBC subtype of breast cancer tissues and provided the first evidence for the poor prognostic significance of B3GALT5 expression in early stage breast cancer." (PMID 33413566, 2021). "Both breast cancer cells and cancer stem cells (BCSCs) were used to see the in vitro effects of knockdown or overexpression of B3GALT5 on cell migration, invasion, and epithelial-to-mesenchymal transition (EMT)." (PMID 33413566, 2021). "We have demonstrated that high B3GALT5 expression serves as a poor prognostic marker for breast cancer patients including those with early stage diseases." (PMID 33413566, 2021). "In the present study, we provide the first evidence for the predictive value of B3GALT5 mRNA expression in the outcome of breast cancer patients." (PMID 33413566, 2021). "To elucidate the biological functions of B3GALT5 in breast cancer that contribute to its adverse prognostication, we first evaluated the impacts of B3GALT5 knockdown on migration and invasion of breast cancer cells." (PMID 33413566, 2021). "Studies have shown that B3GALT5 is upregulated in breast cancer and can regulate the expression of zinc finger E‐box binding homeobox transcription factor 1 (ZEB1) as well as the activation of β‐catenin nuclear translocation, promoting the progression of breast cancer metastasis." (PMID 39224045, 2024). "The adverse impact of high expression of B3GALT5 found on RFS is consistent with Kaplan–Meier analysis using GSE1456 database, which reveals that breast cancer patients with higher B3GALT5 expression has shorter RFS than those with low B3GALT5 expression (P = 0.007)." (PMID 33413566, 2021). "Moreover, we provided the first evidence for the important role of B3GALT5 in lymph node and lung metastasis of breast cancer, using PDX-derived BCSCs implantation model." (PMID 33413566, 2021). "Once the prognostic impact of B3GALT5 in early-stage breast cancer could be validated in further large clinical cohort, B3GALT5 might provide a novel simple and feasible candidate gene for predication of recurrent risk of ESBC." (PMID 33413566, 2021). "However, little is known regarding the clinical relevance of B3GALT5 in breast cancer subgroups and its biological function." (PMID 33413566, 2021).
breast carcinoma (continued). "We then examined the effects of overexpression of B3GALT5 on the migration of breast cancer cells." (PMID 33413566, 2021). "B3galt5 has been associated with cancer-related proteins’ glycosylation due to its ability to catalyzes the galactosylation of glycosphingolipid globoside-4 (Gb4) to form globoside-5 (Gb5), which also known as SSEA3, a common cancer-specific marker highly expressed in breast cancer stem cells." (PMID 39004626, 2024). "Therefore, to investigate whether high expression of B3GALT5 was a significant predictor of recurrence of breast cancer, we performed Kaplan–Meier analysis on 202 breast cancer patients." (PMID 33413566, 2021). "This is, to our knowledge, the first report linking B3GALT5 to EMT and β-catenin/ZEB1 axis in breast cancer." (PMID 33413566, 2021). "In this study, we aimed to delineate the clinical significance of B3GALT5 and to investigate its involvement in EMT and BCSCs of breast cancer." (PMID 33413566, 2021). "B3GALT5 and FUT1/FUT2 have been known to be involved in the biosynthesis of Globo H in breast carcinoma cell lines." (PMID 32237061, 2020). "Higher expression of B3GALT5 in 202 breast cancer tissues, especially in adjacent non-tumor tissue, correlated with poor clinical outcomes including shorter OS and RFS in all patients, especially those with early stage breast cancer." (PMID 33413566, 2021). "Paired tissues (tumor part and adjacent non-tumor part) from a cohort of 202 women with breast cancer were used to determine the expression levels of B3GALT5 mRNA by qRT-PCR." (PMID 33413566, 2021). "Mechanistically, we found B3GALT5 could regulate cell proliferation, migration, and invasion through EMT activator ZEB1 in breast cancer cells as well as other properties of BCSCs, such as mammosphere formation, tumor initiation, and metastasis." (PMID 33413566, 2021). "Our results demonstrated the value of B3GALT5 as a prognostic marker of breast cancer, especially among the early stage patients, and its crucial roles in regulating EMT, cell migration, and stemness thereby promoting breast cancer progression." (PMID 33413566, 2021). "The B3GALT5 mRNA levels in tumor and adjacent non-tumor tissue were shown according to different molecular subtypes of breast cancer." (PMID 33413566, 2021). "Notably, we found the expression of B3GALT5 in adjacent non-tumor part of the breast cancer tissue to be more significantly correlated to clinical outcome when compared to the tumor part." (PMID 33413566, 2021). "Our studies have provided novel finding that B3GALT5 plays a role in facilitating lymph node and lung metastasis through β-catenin/ZEB1 pathway, suggesting B3GATL5 might be potential target for tackling BCSCs, cell proliferation, and EMT in breast cancer." (PMID 33413566, 2021).
colon cancer (7 papers, 2014 to 2022). "While the tissue and individual levels of each transcript are very heterogeneous, significant cancer-associated differences are not reported, except for ST6GALNAC6 and, paradoxically, B3GALT5, which is dramatically down-regulated in colon cancer." (PMID 32527016, 2020). "Colon cancer cells down regulate the biosynthesis of all such antigens due to the silencing of B3GALT5." (PMID 32527016, 2020). "Expression of B3GALT5-LTR in colon tissue contributes up to 74% of the total B3GALT5 expression, and we found that B3GALT5-LTR accounted for ~80% of the total expressed B3GALT5 in the colon cancer cell line HT29." (PMID 31936807, 2020). "The situation is different in colon cancer, where the dramatic down-regulation of B3GALT5 results in undetectable type 1 chain antigens, particularly CA19.9." (PMID 32527016, 2020). "B3GALT5 was found to be down-regulated in colon cancer cell lines, but up-regulated upon CaCo2 cell differentiation." (PMID 30909444, 2019). "At least in colon cancer, this view is in sharp contrast to the finding that the enzymatic machinery is impaired in the synthesis of this antigen because of the down-regulation of the key enzyme B3GALT5." (PMID 32527016, 2020). "However, differential expression of disialyl-Lewis a is not known in organs other than the colon, and colon cancer is associated with a strong down-regulation of B3GALT5, the key enzyme in the synthesis of all Lewis type 1 antigens, including sLea." (PMID 28241499, 2017). "For colon cancer, identified biomarkers are CD15, CD104, CD324, CD326, CD49f, and for renal cancer, CD24, CD26, CD106 (VCAM1), EGFR, SSEA-3 (B3GALT5), SSEA-4 (TMCC1), TIM1 (HAVCR1), and TRA-1-60R (PODXL)." (PMID 36221114, 2022). "More recent data obtained by dot-blotting and immunofluorescence indicated that, consistent with the down-regulation of B3GALT5, the CA19.9 antigen was almost undetectable in colon cancer." (PMID 32527016, 2020). "Conversely, the B3GALT5 transcripts are down-regulated in colon cancer, where type 1 Lewis antigens are scarcely or not detectable." (PMID 28241499, 2017).
hepatocellular carcinoma (4 papers, 2017 to 2023). A malignant tumor that arises from hepatocytes. "In line, FUT1 and B3GALT5 appeared as promising genes associated with the GSLs investigated in this hepatocellular carcinoma study and were further suggested as specific targets for therapeutic intervention." (PMID 33418847, 2021). "B3GALT5 (beta-1.3-galactosyltransferase 5) has been identified as a predictor of postoperative recurrence and survival in patients with hepatic carcinoma and its high expression has been associated with advanced stages and poor outcome." (PMID 29681787, 2018). "Following an examination of the gene expression of their biosynthetic enzymes, FUT1, FUT2, B3GALT5, and ST3GAL2 in hepatocellular carcinoma tissue samples, using RT-qPCR, revealed an association of FUT1 or B3GALT5 expression with advanced stages." (PMID 33418847, 2021). "In this study, we examined the expression of their biosynthetic enzymes, FUT1, FUT2, B3GALT5 and ST3GAL2, in 135 hepatocellular carcinoma (HCC) tissues by qRT-PCR." (PMID 28883415, 2017).
pancreatic cancer (2 papers, 2015 to 2024). "B3galt5 can also catalyze the synthesis of tumor markers CA19-9, which plays an important role in the development of pancreatitis and pancreatic cancer in mice." (PMID 39004626, 2024).
Cerebellar hypoplasia (1 paper, 2023). Cerebellar hypoplasia is a descriptive term implying a cerebellum with a reduced volume, but a normal shape and is stable over time. "Finally, B3galt5 is linked to cerebellar development in a mouse model of cerebellar hypoplasia." (PMID 36995257, 2023).
colitis (1 paper, 2024). Inflammation of the colon. "Adenovirus-mediated expression of B3galt5 is sufficient to rescue Il22Ra1IEC mice from DSS colitis." (PMID 38733584, 2024). "The intestinal epithelial target of IL-22 is MATH1+ cells, which regulate B3galt5 expression (mainly goblet cells) and induce epithelial regeneration (MATH1+ progenitor cells) to protect from the development of DSS colitis." (PMID 38733584, 2024). "Since we observed reduced expression of the B3galt5 gene that promotes mucin type-O glycosylation, we wanted to explore if IL-22Ra1 signaling in MATH1+ cells (predominantly goblet cells in the colon) induces B3galt5 expression and protects mice from DSS-induced colitis." (PMID 38733584, 2024).
colon adenocarcinoma (1 paper, 2024). "In addition, B3galt5 mRNA and protein expression were significantly upregulated after PXR activation by either TBC or rifampicin in LS174T cells, a human colon adenocarcinoma cell-line." (PMID 39004626, 2024).
influenza (1 paper, 2024). An acute viral infection of the respiratory tract, occurring in isolated cases, in epidemics, or in pandemics; it is caused by serologically different strains of viruses (influenzaviruses) designated A, B, and C, has a 3-day incubation period, and usually lasts for 3 to 10 days. "The lead variant at this locus (rs2837113) is a sentinel eQTL for B3GALT5 in skin and salivary gland tissue, with the rs2837113:A influenza-protective allele associating with higher gene expression." (PMID 39103650, 2024). "Genome-wide analyses identify variants in B3GALT5 and ST6GAL1 associated with influenza susceptibility." (PMID 39103650, 2024). "For these experiments, we focused on two likely effector genes of influenza-associated variants—ST6GAL1 and B3GALT5—because of their potential role in a critical step of influenza virus infectivity, that is, modulation of α-2,6-linked sialic acid abundance at the cell surface." (PMID 39103650, 2024). "Of the four likely effector genes of the influenza loci, ST6GAL1 and B3GALT5 are strong biological candidates (ADIPOQ and IGSF5 are discussed in the Supplementary Note)." (PMID 39103650, 2024).
Insulin resistance (1 paper, 2024). Increased resistance towards insulin, that is, diminished effectiveness of insulin in reducing blood glucose levels. "In whole-body B3galt5 knockout mice, we found aggravated obesity, insulin resistance and tissue inflammation upon HFD challenge." (PMID 39004626, 2024). "In summary, our data demonstrated that selectively activation of intestinal PXR alleviated diet induced obesity and insulin resistance by upregulating intestinal B3galt5." (PMID 39004626, 2024). "Together, these findings demonstrate that whole-body B3galt5 deficiency sensitizes mice to HFD-induced obesity, insulin resistance and inflammation." (PMID 39004626, 2024). "To further test the role of B3galt5 in metabolic diseases, we generated whole-body B3galt5 knockout mice and found exacerbated obesity, insulin resistance, and inflammation when challenged with high-fat diet." (PMID 39004626, 2024). "When challenged with HFD, B3galt5−/− mice showed impaired glucose tolerance and insulin resistance as compared to WT mice." (PMID 39004626, 2024). "In this study, we provide the first evidence that selective activation of intestinal PXR can alleviate diet-induced obesity and insulin resistance by upregulating intestinal B3galt5 expression." (PMID 39004626, 2024). "B3galt5 is also responsible for the galactosylation of GlcNAc-based acceptors and glycosphingolipids (GSLs), which are known to be involved in the pathogenesis of insulin resistance in type 2 diabetes." (PMID 39004626, 2024). "We also uncovered a role for B3galt5 as a downstream target gene of PXR in regulating obesity, insulin resistance and systemic inflammation by influencing O-glycosylation of colonic mucus." (PMID 39004626, 2024). "Whole-body and intestinal-specific knockout of B3galt5 both aggravated HFD-induced obesity, insulin resistance, and inflammation." (PMID 39004626, 2024). "B3galt5 knockout exacerbates HFD-induced obesity, insulin resistance and inflammation." (PMID 39004626, 2024). "B3galt5 knockout also abolished the protective effects of TBC on obesity and insulin resistance." (PMID 39004626, 2024).
liver steatosis (1 paper, 2024). "Furthermore, B3galt5−/− mice displayed more severe liver steatosis as shown by the elevated serum ALT/AST level and hepatic lipid deposition." (PMID 39004626, 2024).
lung adenocarcinoma (1 paper, 2025). A carcinoma that arises from the lung and is characterized by the presence of malignant glandular epithelial cells. "CA19-9 pathway bioinformatics: CA19-9 synthesis relies on FUT3/B3GALT5; FUT3 is elevated in CA19-9-high cancers and associates with poorer prognosis in PDAC and lung adenocarcinoma." (PMID 41361823, 2025).
male reproductive system diseases (1 paper, 2023). "Utilizing the CTD database, we demonstrated that the five hub genes (CD300LB, CMKLR1, CCR4, B3GALT5, and CTSK) significantly affected male reproductive system diseases." (PMID 37152990, 2023).
Obesity (1 paper, 2024). Accumulation of substantial excess body fat. "To demonstrate why B3galt5 deficiency aggravates obesity and other metabolic disorders, we tested the integrity of the intestinal barrier in B3galt5 knockout mice." (PMID 39004626, 2024). "To understand the possible mechanism of B3galt5 deficiency-aggravated obesity, we examined the changes of intestinal permeability by FITC-dextran gavage in WT and B3galt5−/− mice." (PMID 39004626, 2024). "Together, these results indicate that B3galt5 regulates obesity by influencing mucin O-glycosylation; B3galt5 deficiency disrupts mucin O-glycosylation, sensitizes mucus for proteolytic degradation, thus impairing the intestinal permeability." (PMID 39004626, 2024). "Our results suggest the intestinal-selective PXR activation regulates B3galt5 expression and maintains metabolic homeostasis, making it a potential therapeutic strategy in obesity." (PMID 39004626, 2024). "Both the mRNA and protein levels of intestinal B3galt5 were observed remarkably decreased in HFD-induced obesity mice and ob/ob mice, as well as high fructose and high cholestrol-induced mouse model." (PMID 39004626, 2024). "Taken together, these results suggest that the beneficial effects of TBC depend on B3galt5, confirming B3galt5 is the messager conducting intestinal PXR function and the PXR-B3galt5 axis is vital for intestinal barrier maintenance, thus preventing the occurrence of obesity and inflammation." (PMID 39004626, 2024). "Thus, we have provided proof-of-concept evidence that modulation of intestinal mucus barrier by targeting intestinal PXR or B3galt5 is an attractive strategy for the prevention and therapy of obesity and related metabolic disorders." (PMID 39004626, 2024). "Our results so far have supported that B3galt5 is a direct target gene of intestinal PXR and regulates the progression of obesity." (PMID 39004626, 2024).